RNU6-94P (RNA, U6 small nuclear 94, pseudogene)
Gene: Small nuclear RNA gene on chromosome 15 (50,347,423 to 50,347,529, reverse strand). Ensembl gene ENSG00000271819.
Homologues: Orthologues: chimpanzee U6 (99% identical), macaque U6 (91% identical), rabbit U6 (76% identical), dog U6 (75% identical). Paralogues in human: RNU6-86P (91% identical), RNU6-774P (89% identical), RNU6-140P (88% identical), RNU6-16P (88% identical), RNU6-21P (88% identical), RNU6-33P (88% identical), RNU6-38P (88% identical), RNU6-480P (88% identical), RNU6-890P (88% identical), RNU6-1 (87% identical), RNU6-11P (87% identical), RNU6-144P (87% identical), and 1289 more.